MMP9 (matrix metallopeptidase 9)
Diseases named in the same sentence as MMP9 in open-access papers (continued):
Sharing a sentence is not in itself a finding about the gene and the disease.
infection (continued). "The formation and development of new blood vessels in the cornea are mediated by a complex array of cellular and molecular factors, and VEGF and MMP-9 are known to have important roles in angiogenesis and in NV after corneal injury and infection." (PMID 37238701, 2023). "ELISA kits were used to detect serum levels of KLK12, MMP-1, and MMP-9 in mice with different infection doses, and the results were consistent with findings in lung tissues." (PMID 36293113, 2022). "In comparison to fish sampled before infection, il-1β, tnf-α1, tnf-α2, mmp-9, and socs-3 expression shows a trend to reach higher levels in fish sampled on the time frame between 6 and 24 h post-infection." (PMID 35328519, 2022). "Using these two infection models, we confirmed that the transcription levels of KLK12, MMP-1, and MMP-9 in lung tissue were positively correlated with the initial dose of infection." (PMID 36293113, 2022). "Immunostaining identified metalloproteinase 9 (MMP9) in neutrophils present among necrotic hepatocytes at the first points of infection." (PMID 36091027, 2022). "MMP-9 expression is significantly increased by infection with respiratory viruses, including IAV, SARS-CoV-2, HRV, and RSV, and is positively correlated to the severity of the diseases." (PMID 36142454, 2022). "A few genes, namely il1b, il12a, cxl34a.4, saa, irg1l, mmp9 and cebpb, were significantly upregulated by infection in the common 151 signature set." (PMID 35933481, 2022). "TNF-α, which is increased during IAV infection, induces MMP-9 secretion in neutrophils, causing the ECM collapse and resulting in an increase in the influx of immune cells to the site of infection, thereby increasing the severity of IAV infection." (PMID 36142454, 2022). "FPS-ZM1 treatment also reduced levels of MMP-9 on day 2 after infection and EPO on day 4 after infection." (PMID 35076028, 2022). "Serum KLK12, MMP-1, and MMP-9 were significantly upregulated in mice after M. bovis infection, and the degree of upregulation was positively correlated with the initial infection dose." (PMID 36293113, 2022). "MMP-9 secretion during the acute phase of infection led to the degradation of ECM, which facilitates leukocyte transmigration from the vasculature to tissues." (PMID 35892136, 2022). "MMP-9 is a novel marker of infection that relies on the assistance of metal ions such as Ca2+ and Zn2+ to exert extracellular matrix degradation." (PMID 36159580, 2022). "To confirm the role of this epigenetic modification in the modulation of MMP-9 expression following M. pneumoniae infection, we examined the acetylation status of histones H3 and H4 after M. pneumoniae-infection." (PMID 35892136, 2022). "Some neutrophils secreted MMP9 from the earliest points of infection, indicating degradation of the extracellular matrix in regions of histolysis and a possible chemoattraction of hematopoietic stem cells to the liver." (PMID 36091027, 2022). "Previously, there was a report of upregulation of MMP-2 and MMP-9 during the infection of host cells with B. cenocepacia." (PMID 35113856, 2022). "At the beginning of infection, significant up-regulation of mmp-9 expression was detected in the foregut, midgut, hindgut, spleen, and head kidney, suggesting the important role of Mmp-9 in the innate immune response." (PMID 36466906, 2022). "A significant reduction in the expression of MMP-1 and MMP-9 was observed in KLK12 knockdown RAW264.7 cells at 24h post-infection with M. bovis compared to control cells." (PMID 36293113, 2022). "In agreement with our imaging studies, MMP-9 was significantly elevated on day 2 after infection in vehicle-treated mice compared with mock-infected controls." (PMID 35076028, 2022). "Genes coding for MMP-9 were significantly upregulated in the infection group compared with their controls (4.9-fold change, p < 0.001)." (PMID 32865714, 2021).
infection (continued). "In the kidneys of immunosuppressed mice infected with Acanthamoeba spp., there was also a decrease in pro-MMP-9 levels during the course of the infection." (PMID 34205319, 2021). "RT-PCR validation also found significant higher MMP-9 mRNA levels in patients in the infection group (p = 0.001)." (PMID 32865714, 2021). "Infection with H. pylori led to a strong induction of MMP-9 activity as shown by the proteolytic 90 kDa band in supernatants of infected cells." (PMID 34742300, 2021). "Infection with F. nucleatum induced key molecular players, such as cyclin D1 and matrix metalloproteinase-9 (MMP-9), which are involved in oral tumour growth and invasiveness." (PMID 34774023, 2021). "The validation using Elisa kits found that key proteins Mmp9 and S100a8/a9 were significantly increased in mouse lung tissue during A. baumannii clearance (Infection versus Control, nominal p < 0.05)." (PMID 34025711, 2021). "For example, MMP-9 knockout mice develop more severe distant organ damage during infection and enhanced allergen-induced airway inflammation." (PMID 33628393, 2021). "In the kidneys of immunocompetent mice infected with Acanthamoeba spp., the MMP-9/NGAL ratio decreased with the duration of the infection (H = 25, p < 0.001)." (PMID 34205319, 2021). "The research results obtained by the author indicate that the concentrations of MMP-8, MMP-9 (and others) were higher in the case of suspected infection compared to the control group and also in the case of intrauterine infection." (PMID 34501333, 2021). "In the kidneys of immunocompetent mice infected with Acanthamoeba spp., the level of pro-MMP-9 decreased with the duration of the infection (H = 22.96, p <0.001)." (PMID 34205319, 2021). "In vitro studies in human astrocytic and microglial cells with human coronavirus showed an increase in the levels of MMP2 and MMP9 in infection." (PMID 32595353, 2020). "After adjusting for confounding variables, we found that lower GCS at hospital admission (p = 0.049), infection during the ICU stay (p = 0.031) and plasma MMP-9 levels (p = 0.011) were variables independently associated with poor outcome (death)." (PMID 33053032, 2020). "In contrast, testes of IFNAR1-blocking antibody treated-MMP9-/- mice harbored a significantly lower viral load than those of treated WT mice at 10 days post infection (dpi)." (PMID 32302362, 2020). "This confirmed what was observed in WT C57Bl/6 mice, i.e., the exacerbated effect of IAV on PAO1 infection and the key involvement of metalloproteases, including MMP-9." (PMID 32117268, 2020). "Western blot analysis revealed that the levels of p-ERK1/2, MMP-2, and MMP-9 were remarkably increased after infection with SPARC for 72 h." (PMID 32670867, 2020). "RSV increases the expression of matrix metalloproteinase-9 (MMP-9), which augments the influx of neutrophils to the site of infection." (PMID 32726921, 2020). "Ad-uPAR-MMP9 infection was shown to downregulate uPAR and MMP9 protein levels and inhibit angiogenesis in human lung tumor cells in vitro." (PMID 33167307, 2020). "Matrix metalloproteinase 9 (MMP-9) plays an important role in inflammatory and pathological processes by enabling the inflow of leukocytes to the site of infection or tissue damage." (PMID 32190734, 2020). "Our results showed that the level of MMP-9 was markedly upregulated due to infection with S. mansoni." (PMID 30606163, 2019). "During a CVB3 murine infection, MMP9 was found to prevent virus propagation in the heart, promote immune infiltration and remodeling, and preserve cardiac output–product of the heart rate and the stroke volume." (PMID 31394726, 2019). "It was shown that activation and cellular export of MMP-9 led to the cleavage of occludin during infection by hepatitis C virus." (PMID 30805031, 2019). "Previously, we have demonstrated that upon infection of LX-2 cells, B. abortus inhibits MMP-9 secretion and induces concomitant collagen and TGF-β1 secretion." (PMID 32038610, 2019).
infection (continued). "Merged images showed the expression of MMP-9 and occludin at the same sites around the epithelium in the choroid plexus after infection with A. cantonensis." (PMID 31415587, 2019). "Although MMP-2 and MMP-9 were both found to be expressed at the site of infection, only in 36% of patients with M. mycetomatis the activated form of MMP-9 was present." (PMID 31295246, 2019). "EsxA has been shown to induce expression of matrix metalloproteinase-9 (MMP9), which recruits additional phagocytes to the site of infection and facilitates its spread to new cells." (PMID 30967867, 2019). "Western blot analysis showed that the expression of p-FAK, p-PI3K, p-Akt, MMP-2, and MMP-9 was increased in corneal tissue at 2 days after infection and decreased from 7d to 2d, 14d, and 28d." (PMID 31061823, 2019). "The expression of p-Akt, MMP-2, and MMP-9 at 7 days after infection was significantly higher than that at 0 days (P< 0.05)." (PMID 31061823, 2019). "Further experiments revealed that CA16 infection promoted the degradation of junctional complexes (Claudin4, Claudin5, VE-Cadherin, and ZO-1), likely by downregulating miR-1303 and upregulating MMP9." (PMID 30228270, 2018). "Coincidently, CA16 infection induced increased permeability of the BBB that was accompanied by upregulated MMP9 expression." (PMID 30228270, 2018). "An increased activity of MMP-2 and MMP-9 has been observed in infections of tropical protozoa to the CNS, e.g., Plasmodium falciparum and Trypanosoma brucei gambiense." (PMID 30572657, 2018). "Several MMPs, such as MMP-2 and MMP-9, are important in lung remodeling before and after birth as well as in response to environmental indices, infection, and lung injury." (PMID 30114253, 2018). "infected immunocompetent mice the level of MMP-9 protein in the cerebral cortex was significantly higher than in the control group at the beginning of infection." (PMID 30572657, 2018). "The results showed that CA16 infection induced increased permeability of the BBB accompanied by upregulation of matrix metalloproteinase 9 (MMP9) expression." (PMID 30228270, 2018). "In vitro studies documented infection-induced MMP-9 expression in monocytes and human fetal membranes exposed to different pathogens and Toll-like receptor (TLR) agonists." (PMID 29558521, 2018). "Our results are the first to demonstrate that CA16 infections in HUVECs can decrease the expression of miR-1303, which relieves the inhibitory role in MMP9 release and thus promotes MMP9 expression." (PMID 30228270, 2018). "In contrast, in pBECs from asthmatics, the expression of CD147 increased but miR-22, HDAC4 and MMP-9 expression remained unchanged after infection." (PMID 30068332, 2018). "The reduced number of neutrophils following infection with ΔespO was consistent with lower abundance of Mmp9 and was mirrored by a global decrease in expression of genes encoding AMPs, with the exception of Dmbt1 and Iod1." (PMID 30365535, 2018). "The second profile comprises factors that are increased by infection independently of the viral genotype including sICAM-1 and GM-CSF in both tissues, or G-CSF and MMP-9 only in the placenta." (PMID 30420629, 2018). "Gelatinase B or matrix metalloproteinase-9 (MMP-9) is also induced by SAA1 during infection and inflammation and processes many substrates in the immune system." (PMID 29915572, 2018). "It was observed that miR-1303 expression was reduced, whereas MMP9 expression was elevated in HUVECs following CA16 infections, which was consistent with the high-throughput sequencing data." (PMID 30228270, 2018). "As alveolar macrophages are important to host response to infection and MMP-9 plays a role in tissue injury, regulation of the production of MMP-9 by macrophages has significant implication in pulmonary infections." (PMID 29018444, 2017). "After infection for another 8 weeks, the amount of the active form of MMP9 secreted by HIOECs-Pg-23 was much higher than that secreted by HIOECs-Pg-15." (PMID 28286742, 2017).
infection (continued). "Dysregulation of progesterone, COX-2, PGE2 and PGF2α expression in infected pregnant mice was accompanied by significant remodeling of placental architecture and upregulation of MMP-9 early after infection." (PMID 29176767, 2017). "When the infection of neutrophils occurred in the presence of heme, we observed a mixed pattern hallmarked by a simultaneous increase in MMP-9 levels as well as in MPO and NE activity." (PMID 29218050, 2017). "Heterophils decreased ALB and FN1, and released MMP9 to enable their translocation to the site of infection." (PMID 28623956, 2017). "The mRNA levels of MMP-3, MMP-8, MMP-9, and TIMP-1 were analyzed 12 h after FT explant infection with Ngo strain P9, variant 17 (Pil+Opa+)." (PMID 28932707, 2017). "IAV-induced MMP-9, TNF, and IL-6 in lungs of MALT1-deficient mice are significantly lower than in wild-type mice after intratracheal infection." (PMID 29018444, 2017). "NF-kB inhibition decreased neutrophil MMP-9 secretion in response to both direct infection and monocyte-dependent networks." (PMID 28173836, 2017). "It was found that knock-out of MMP-9 gene in a mouse model limits infection and damage of intestinal mucosa." (PMID 28978100, 2017). "Mmp9 is a matrix metalloproteinase related to leukocyte migration to infection sites and tissue destruction if it is secreted in excess amounts." (PMID 28542507, 2017). "Ex vivo study can mimic the in vivo model of Mycobacterium tuberculosis infection where MMP-9 levels are known to be elevated due to infection." (PMID 27899068, 2016). "Biochemical markers of tissue damage in CF disease such as MMP-9 activity and protein, TGF-β1 protein and sulphated GAG (sGAG) increased progressively during long-term infection with AA43 and AA44 CF-adapted variants." (PMID 26883959, 2016). "A comparable expression pattern was seen with the matrix metalloproteinase MMP9, a secreted protease that facilitates the migration of leukocytes to sites of infection." (PMID 27303721, 2016). "MMP-9 is released by activated PMNs at the site of infection resulting in tissue injury, and further perpetuation of the vicious cycle of inflammation and tissue destruction." (PMID 27110221, 2016). "The genes used (matrix metallopeptidase 9, olfactomedin 4, NB1 glycoprotein and lipocalin 2) were previously identified as predictive for severity of disease caused by infection with respiratory syncytial virus (RSV)." (PMID 26298058, 2015). "MMP-9 is predominantly secreted by monocytes which are central cells in developing immune response to infection." (PMID 25931987, 2015). "Using a single gene knockout strategy in our in vivo model, we found that RSV titer was reduced greater than 2 logs in the MMP-9 knockout mice during the acute phase of infection (day 2–4)." (PMID 26264019, 2015). "Our data suggests a model whereby the pathogenesis of S. Typhimurium involves manipulation of the host innate immune and protease system, here illustrated by PPARγ, Lcn2 and MMP-9, to establish colonization and infection within the host." (PMID 24465207, 2014). "The activity of proMMP-9 increased by ∼6 fold in PPARγVillinCre- mice and ∼15 fold in PPARγVillinCre+ mice after infection, while MMP-9 activity rose from ∼4 fold in PPARγVillinCre- mice to ∼7 fold in PPARγVillinCre+ mice after infection." (PMID 24465207, 2014). "In infection-induced preterm birth, the increase in pro-inflammatory cytokines, chemokines, and prostaglandins all lead to increased expression of MMP-9." (PMID 25238390, 2014). "Robust changes in expression of several genes was evident 7 days post-infection; expression of Col1a1, Col1a2, Col3a1, Mmp2, Mmp9 and Lox was significantly increased while expression of Timp3 was significantly decreased." (PMID 24950301, 2014). "Preterm fetal membranes with active infection treated with silibinin showed a decrease in IL-6, IL-8 and MMP-9 expression." (PMID 24647589, 2014).
infection (continued). "During the later stages of infection (day 21) higher pro-MMP9 levels were found in uterine horns of IL-17-/- mice." (PMID 24073293, 2013). "The objective of this study was to investigate the role of the matrix metalloproteinase (MMP)-9 in the degradation of tight junction protein during infection with rat nematode lungworm Angiostrongylus cantonensis." (PMID 23505411, 2013). "These include three proteases that are upregulated during the course of infection: the matrix metalloprotease MMP9, the serine proteases neutrophil elastase (ELANE), and cathepsin G (CTSG), as well as the protease inhibitor SERPINB1." (PMID 23638192, 2013). "This delay in elaboration of pro MMP-9 and its related gelatinase activity is likely due to the arrival of other inflammatory cells capable of producing MMP-9, namely macrophages, at the later stage of infection." (PMID 24073293, 2013). "Gr1+ granulocytes in upper genital tract tissues are the major source of MMP9, which was increased in oviducts of WT mice early in infection." (PMID 24073293, 2013). "Late in the infection (day 21), the trend was reversed and higher levels of pro-MMP9 were found in the uterine horns of IL-17-/- mice compared to WT mice (p<0.05)." (PMID 24073293, 2013). "In this study, we present evidence indicating that upon infection with B. abortus, as well as other Brucella species, astrocytes secrete MMP-9 to culture supernatants." (PMID 23587438, 2013). "By all methods employed, the magnitude of MMP-9 released to culture supernatants was directly related to the multiplicities of infection (MOI) used to infect cells." (PMID 23587438, 2013). "Astrocyte infection resulted in an increased MMP activity that was detected by zymography in the supernatants of infected cells at 48 hours post infection, which according to the molecular weight of the band corresponded to MMP-9." (PMID 23587438, 2013). "Infection with C. rodentium resulted in activation of MMP-9, as demonstratedby zymography of colonic tissue." (PMID 22694805, 2012). "The expression of matrix metalloproteinase 9 (Mmp9) in macrophages of B6 mice was lower than that in A/J mice post-infection." (PMID 22384161, 2012). "Ly6G+ cells were significantly decreased in both BAL and lung from the Mmp9−/− mice 6 days after infection." (PMID 22496659, 2012). "Since neutrophil numbers were significantly increased following high dose infection and this population appeared to be the predominant source of MMP9 in the lung after infection, we sought to identify the direct function of MMP9 in this cell population." (PMID 22496659, 2012). "Pharmacological approaches suggest that targeting MMP-9 and its specific upstream signaling components should yield useful therapeutic targets for CNS inflammatory diseases upon infection with gram-positive bacteria." (PMID 22643046, 2012). "In response to tissue inflammation or infection, neutrophil numbers increase in the bone marrow and release proteases, such as, matrix metalloproteinase-9 (MMP-9), neutrophil elastase, and cathepsin G." (PMID 22762001, 2012). "Wild-type and MMP-9−/− mice aged 5–6 weekswere challenged with C. rodentium by orogastric gavage andsacrificed either 10 or 30 days post-infection." (PMID 22694805, 2012). "The MMP-9 levels of the GLY-treated rats were significantly lower than in the placebo group 40 h after infection (P < 0.05)." (PMID 20353584, 2010). "In this study, the placebo and the GLY groups showed equally high levels of MMP-9 24 h after infection." (PMID 20353584, 2010). "Pharmacological approaches targeting MMP-9 and their specific upstream signaling components should yield useful therapeutic targets for CNS inflammatory diseases upon infection with Gram-positive bacteria." (PMID 21092323, 2010). "The lungs were removed 48 hours post-infection and examined for lipocalin 2 and MMP9 (a myeloid marker protein) by immunohistochemical staining and western blotting." (PMID 20633248, 2010).